COL4A5 (collagen type IV alpha 5 chain)
Diseases named in the same sentence as COL4A5 in open-access papers (continued):
Sharing a sentence is not in itself a finding about the gene and the disease.
Alport syndrome (continued). "We treated 129S1/SvImJ background Col4a3−/− Alport syndrome mice, which have a shorter lifespan than C57BL/6 background Col4a5 G5X Alport syndrome mice, with losartan or metformin alone, or in combination, via drinking water from 4 weeks old." (PMID 33782421, 2021). "Observed versus expected likelihood of Glycine substitutions in the COL4A5, COL4A3 and COL4A4 genes in Alport syndrome and Thin basement membrane nephropathy." (PMID 27627812, 2016). "Genetic testing is now the gold standard investigation, with next-generation sequencing of COL4A3, COL4A4, and COL4A5 being recommended in patients with no family history of Alport syndrome." (PMID 41299396, 2025). "The three collagen IV genes involved in Alport syndrome are COL4A3, COL4A4, and COL4A5." (PMID 38745975, 2024). "To investigate the effect of metformin on non-diabetic glomerular disease, we used a mouse model of Alport syndrome (Col4a5 G5X) which were treated with metformin or losartan, used as a control treatment." (PMID 33782421, 2021). "Here, we report a case of Alu exonization resulting from a 367-nt genomic COL4A5 deletion that did not encompass any recognizable transposed element, leading to the Alport syndrome." (PMID 25333070, 2014). "However, recent expert consensus guidelines recommend genetic confirmation as essential, defining Alport syndrome more broadly to include all individuals harboring pathogenic variants in COL4A3, COL4A4, or COL4A5, regardless of their clinical presentation." (PMID 40852417, 2025). "Although this study did not indicate a causal relationship between variants on the COL4A5/COL4A3 gene and familial IgAN, it illustrated that the mutations in the COL4A5/COL4A3 gene may cause a wide spectrum of diseases, not just Alport syndrome." (PMID 38202130, 2023). "A new form of digenic non-Mendelian inheritance of Alport syndrome, with coexisting mutations in COL4A3, COL4A4, or COL4A5 genes, has recently been described, simulating autosomal recessive inheritance (digenic mutations in trans) or autosomal dominant inheritance (mutations in in cis mode)." (PMID 33233744, 2020). "Although mRNA from patient kidney biopsies has abundant COL4A5 expression, the cDNA analysis for COL4A5 by using mRNA from kidney is not a common procedure since we now conduct a genetic analysis first approach for the diagnosis of Alport syndrome without performing a kidney biopsy." (PMID 35211492, 2022). "Mutations in COL4A6 alone have not been related to Alport syndrome, but a COL4A6 mutation is linked to hereditary hearing loss, which is a more restricted symptom compared to Alport syndrome, implying that the Col4a5/Col4a6 complex has a more limited role in BM integrity in humans than in zebrafish." (PMID 26451951, 2015). "Overall, the commonest genes affected in FSGS are COL4A5 (XL Alport syndrome) and COL4A3 and COL4A4 (usually AD rather than the rare AR Alport syndrome) INF2, TRPC6 and ACTN4." (PMID 37578539, 2024). "Kidney organoids derived from COL4A5-mutant iPSCs recapitulated the absence of the mature α3/α4/α5(IV) collagen network in the GBM, successfully modeling phenotype differences between mild and severe Alport syndrome." (PMID 41302105, 2025).
kidney failure (25 papers, 2012 to 2026). An acute or chronic condition that is characterized by the inability of the kidneys to adequately filter the blood. "By incorporating genetic markers such as variants in COL4A3, COL4A4, and COL4A5, our study design can address the variable progression rates from diagnosis to renal failure." (PMID 40165927, 2025). "The study thus established the natural history of X‐linked AS and correlations with COL4A5 mutations in a large male patient cohort, highlighting that the risk of severe kidney failure and hearing loss varied depending on the mutation type." (PMID 40165927, 2025). "In 46, XX individuals with heterozygous variants in COL4A5, the chance of kidney failure by age 60 years is 15%–30%." (PMID 40317772, 2025). "Among these AS families, renal failure was most frequently observed in patients with variants of COL4A5 gene." (PMID 38433557, 2024). "Nonetheless, it was shown that COL4A5 variants with potential for disease were often found in renal failure queues and normal reference data, suggesting that the occurrence rate of XLAS was around 1/5,000." (PMID 39184349, 2024). "In contrast, no clear genotype–phenotype correlation has been reported among females with heterozygous variants in COL4A5 and their age at kidney failure." (PMID 37893135, 2023). "Promising results were found in vitro and in an animal model with AS in which the exon 21 of COL4A5 gene skipping was associated with a less severe phenotype with later age of renal failure." (PMID 36982595, 2023). "For women with a COL4A5 variant, the risk of renal failure by the age of 60 is approximately 15-30%." (PMID 38021591, 2023). "In men with a COL4A5 variant, around 90% will suffer from kidney failure demanding replacement therapy by the age of 40." (PMID 38021591, 2023). "Pathogenic COL4A5 variants that resulted in a Gly substitution with a highly destabilising residue reduced the median age at kidney failure by 7 years (p = 0.002), and age at hearing loss diagnosis by 21 years (p = 0.004)." (PMID 35177655, 2022). "Average age at kidney failure in males with pathogenic COL4A5 variants in LOVD in 2021 compared with 2016." (PMID 35602506, 2022). "This is consistent with our findings in COL4A5, where these features were associated with later and earlier ages at kidney failure respectively." (PMID 35177655, 2022). "Because pathogenic COL4A5 variants result in kidney failure in most males the genotype-phenotype relationship is understood best in males with X-linked disease." (PMID 35602506, 2022). "It has been more difficult to correlate COL4A5 variants in women with age at kidney failure because of random X chromosome inactivation." (PMID 35602506, 2022). "Other studies have found that COL4A5 deletions, insertions, and nonsense variants, are associated with early onset renal failure." (PMID 27627812, 2016). "The age at onset of renal failure was available for 237 COL4A5 mutations (12%) and the mean age was 24.3 years." (PMID 27627812, 2016). "Some studies have suggested that pathogenic changes in the first 20 exons of COL4A5 and hence the amino terminus of the collagen IV α5 chain is associated with milder disease and others have found more severe disease with earlier onset kidney failure." (PMID 35602506, 2022). "Many studies of COL4A5 variants in males have found that severe changes (large rearrangements, nonsense and frameshift, and splicing variants) are associated with an earlier age at kidney failure than missense changes." (PMID 35602506, 2022). "In summary there may be a similar genotype-phenotype correlation in women with pathogenic COL4A5 variants and proteinuria as occurs in men with kidney failure but with a smaller effect that requires a larger cohort for its demonstration." (PMID 35602506, 2022). "In the COL4A5 variants in the LOVD database, the mean age at kidney failure for all males was 25.1 ± 10.6 years (n = 326)." (PMID 35602506, 2022).
kidney failure (continued). "Our report highlights that females heterozygous for the COL4A5 (c.1633G > A, p.Gly545Ser) variant are not merely asymptomatic carriers but may develop renal failure, as illustrated by the disease progression in the maternal grandmother in this pedigree." (PMID 42255916, 2026). "Moreover, patients harboring truncating COL4A5 variants were more likely to develop kidney failure earlier than patients with nontruncating variants (HR: 2.59, 95% CI: 1.79–3.76)." (PMID 40630291, 2025). "For COL4A5, renal failure occurred sooner with non-missense than missense variants (p<0.01)." (PMID 27627812, 2016). "Alport disease in humans, which usually results in proteinuria and kidney failure, is caused by mutations to the COL4A3, COL4A4, or COL4A5 genes, and absence of collagen α3α4α5(IV) networks found in mature kidney glomerular basement membrane (GBM)." (PMID 23236390, 2012). "Eight (24%) of the 34 heterozygous COL4A3 and COL4A4 carriers developed renal failure at a mean age of 57 years, with a significantly lower risk than hemizygous COL4A5 or double heterozygous COL4A3/COL4A4 carriers (p < 0.01), but not different from that of the heterozygous COL4A5 females (p = 0.6)." (PMID 33369211, 2021).
Nephropathy (15 papers, 2014 to 2025). A nonspecific term referring to disease or damage of the kidneys. "The proband has also progressed to ESRD so far, and the younger brother also has kidney damage, the kidney damage caused by the COL4A5 mutation is of serious phenotype in males." (PMID 38671472, 2024). "Known potential treatment strategies for COL4As-related nephropathy include angiotensin-converting enzyme inhibitors, which may delay disease progression, the Nrf2 activator bardoxolone, and gene therapy for COL4A5 mutations." (PMID 40753325, 2025). "While COL4A5 gene variants cause X-linked AS, mutations in COL4A3 or COL4A4 genes (both located on chromosome 2) are associated with autosomal recessive AS, autosomal dominant AS, and thin basement membrane nephropathy." (PMID 41306271, 2025). "These two cases of COL4A5-related nephropathy were remarkable for various reasons." (PMID 38668984, 2024). "For this reason, we need to change the definition of AS to include all cases with nephropathy caused by COL4A3, COL4A4, or COL4A5 gene variants and eliminate the disease entity of TBM; this will allow patients to avoid missing the opportunity to start appropriate treatment as early as possible." (PMID 30128941, 2019). "Furthermore, the study suggests that coinheritance of COL4A5 and MYO1E variants predicts an increased severity of kidney diseases, and a novel COL4A5 c.3097G>C variant was identified together with MYO1E variants in a patient with presumed nephropathy and no confirmed diagnosis." (PMID 41300747, 2025).
hearing loss (13 papers, 2015 to 2025). "Similar to our findings, these patients presented with fewer incidences of KF and hearing loss compared with patients with other likely pathogenic COL4A5 variants, indicating lower expressivity." (PMID 40485705, 2025). "This may suggest that AMMECR1 is pathogenically implicated in hearing loss, either alone, or as a modifier gene to COL4A5 due to their direct protein–protein interaction." (PMID 27811305, 2017). "Several collagen genes (COL1A1, COL1A2, COL2A1, COL4A3, COL4A4, COL4A5, COL11A1, and COL11A2) are associated with hereditary syndromic hearing loss." (PMID 33848312, 2021). "Females with a severe pathogenic COL4A5 variant have an increased risk of proteinuria, and hearing loss is common but lenticonus does not occur." (PMID 35602506, 2022). "No studies in women with pathogenic COL4A5 variants have demonstrated any genotype-phenotype correlations for hearing loss or ocular abnormalities." (PMID 35602506, 2022). "For hearing loss, because some studies have reported its association with the genotypes, its presence might serve as an alternative to the pathogenic variants in COL4A5 when genetic testing is not available, as in our clinical-only model." (PMID 40630291, 2025). "Among the seven patients with identified COL4A5 variants who were initially diagnosed of FSGS, three children developed into KF without hearing impairment or ophthalmological abnormalities." (PMID 39363361, 2024).
focal segmental glomerulosclerosis (12 papers, 2018 to 2025). A renal disorder characterized by sclerotic lesions in the glomeruli. "Heterozygous COL4A3 or COL4A4 variants, or heterozygous COL4A5 in women can present with a range of histological and phenotype features variably, including hematuria, proteinuria, focal segmental glomerulosclerosis, and chronic kidney disease." (PMID 37180518, 2023). "Among the most common pathogenic variants were COL4A3, COL4A4, COL4A5, and other genes that are implicated in focal segmental glomerulosclerosis." (PMID 38993907, 2023). "While the first patient underwent WES, which detected a pathogenic variant in COL4A5, the second patient had a nephrotic syndrome/focal segmental glomerulosclerosis sequencing panel that revealed a likely pathogenic variant in COL4A4." (PMID 30002862, 2018). "Interestingly, the proband’s mother, a heterozygous carrier of the same COL4A5 variant, presented PKD, IgA glomerulonephritis, and focal segmental glomerulosclerosis (FSGS)." (PMID 40565535, 2025). "Pathogenic variants in the COL4A3, COL4A4, and COL4A5 genes lead to collagen IV (COL4) nephropathies, including Alport syndrome (AS), thin basement membrane nephropathy, and familial forms of focal segmental glomerulosclerosis (FSGS)." (PMID 39588246, 2024). "Mutations in COL4A3, COL4A4, or COL4A5—encoding the α3, α4, or α5 (IV) chains, respectively—cause various diseases, including thin basement membrane nephropathy (TBMN), Alport syndrome (AS), and late-onset focal segmental glomerulosclerosis (FSGS)." (PMID 36292665, 2022). "We describe a COL4A5 novel familial frameshift variant (NM_000495.5: c.1095dup p.(Leu366ValfsTer45)), which was associated with AS and PKD in the hemizygous proband, as well as with PKD, IgA glomerulonephritis and focal segmental glomerulosclerosis (FSGS) in the heterozygous mother." (PMID 38790225, 2024).
chronic kidney disease (11 papers, 2020 to 2025). Impairment of the renal function secondary to chronic kidney damage persisting for three or more months. "The variant co-occurred with COL4A5:c.1871G>A, suggesting a potential digenic inheritance pattern in a proband (F060) with chronic kidney disease and a family history of chronic kidney disease." (PMID 40004525, 2025). "As a disease of type IV collagen caused by variants in collagen IV genes (COL4A3, COL4A4, and COL4A5), AS weakens the structural integrity of basement membranes, and leads to chronic kidney disease (CKD), hearing loss, and eye abnormalities." (PMID 40485716, 2025). "Ocular involvement (22.2%) and chronic kidney disease (7.7%) were features only observed in males with COL4A5 variants in our cohort." (PMID 39349776, 2025). "A strong correlation between the type of COL4A5 mutation and the age developing end-stage renal disease in male patients has been found." (PMID 32117450, 2020). "A strong correlation has been found between the COL4A5 mutation type and the age developing end-stage renal disease in male patients." (PMID 32117450, 2020). "In our study group, both probands with variants in COL4A5 and COL4A3 had a family history of chronic kidney disease." (PMID 40004525, 2025). "COL4A4: collagen 4 alpha 4, COL4A5: collagen 4 alpha 5, ESRD: end-stage renal disease." (PMID 41257164, 2025).
nephrotic syndrome (11 papers, 2013 to 2025). A collection of symptoms that include severe edema, proteinuria, and hypoalbuminemia; it is indicative of renal dysfunction. "This study reported three X-linked dominant Alport syndrome (XLAS) pedigrees with nephrotic syndrome (NS) as the predominant phenotype and analyzed COL4A5 gene alterations." (PMID 39184349, 2024). "His younger brother presented at the age of 6 months with steroid resistant nephrotic syndrome and was also hemizygous for the same COL4A5 variants." (PMID 27725732, 2016). "New mutations c.4435_4445del and c.1584_1587+6del enriched the COL4A5 gene mutation spectrum, and carriers of these two mutation sites and c.5020C>T may present nephrotic syndrome as the predominant clinical symptom." (PMID 39184349, 2024). "For instance, it has been reported in the last two years that LAMA5 variants are co-inherited with COL4A5 variants in familial hematuria, and such co-inheritance might affect pediatric nephrotic syndrome." (PMID 32386536, 2020). "Those who had concomitant COL4A5 and MYO1E mutations presented with nephrotic syndrome and rapidly progressed to ESKD, in contrast to those that only harbored the COL4A5 variant." (PMID 40003707, 2025). "COL4A3, COL4A4 and COL4A5 genes should be included in steroid-resistant nephrotic syndrome genetic panels." (PMID 38780768, 2024). "Using this approach, we found novel or known COL4A3 or COL4A5 mutations in a subset of patients with clinically diagnosed or suspected AS, APOL1 variants associated with FSGS in African Americans and novel mutations in genes associated with nephrotic syndrome." (PMID 24130771, 2013).
glomerular disease (10 papers, 2013 to 2025). "Recently, using minigene assay, we have detected splicing abnormalities in the COL4A5 gene as a cause of glomerular disease." (PMID 32201916, 2020). "Although FSGS is frequently considered a primary glomerular disease, it can also represent the histological manifestation of genetic disorders affecting the GBM, including mutations in COL4A3, COL4A4 or COL4A5 genes." (PMID 41562995, 2025). "In our family, four patients presented with heterogeneous clinical phenotypes of glomerulopathy, while none of them showed any clinical features of either sensorineural hearing loss or typical COL4A5-related ocular abnormalities." (PMID 25110662, 2014).
thin basement membrane nephropathy (9 papers, 2013 to 2025). "The variant c.1871G>A, p.(Gly624Asp) in COL4A5 is described in the literature as a hypomorphic variant associated with thin basement membrane nephropathy (TBMN)." (PMID 31850286, 2019).
deafness (8 papers, 2012 to 2025). An inherited or acquired condition characterized by the complete loss of the ability to hear from one or both ears. "Despite this, it offered valuable insights into the mutation‐dependent progression of AS, highlighting the variable risk of developing end‐stage renal failure and deafness associated with different COL4A5 mutations." (PMID 40165927, 2025). "An identified splice site mutation in COL4A5 was sufficient to explain the development of renal disease, deafness and ocular abnormalities." (PMID 22919268, 2012). "However, in cases of X‐linked AS in males, the type of COL4A5 mutation greatly influences disease progression and the development of serious complications such as end‐stage renal failure and deafness, underlining the importance of early genetic testing and personalized care in this population." (PMID 40165927, 2025). "TMPRSS3, MYO15A, GJB2, SLC26A4 were found to be responsible for deafness in autosomal recessive or sporadic families, while TECTA, WFS1, MYH9, EYA1, COL4A5 and COL11A1 were identified as the responsible genes for deafness in autosomal dominant families." (PMID 23967202, 2013). "TECTA, WFS-1, MYH9, EYA1, COL4A5, COL11A1 were identified as the responsible genes for deafness in autosomal dominant families." (PMID 23967202, 2013).
colorectal cancer (7 papers, 2019 to 2025). A primary or metastatic malignant neoplasm that affects the colon or rectum. "Loss of COL4A5 expression in colorectal cancer is associated with hypermethylation of its promoter region." (PMID 31959204, 2020). "It was also revealed that COL4A5 was down-regulated in colorectal cancer due to the hypermethylation of its promoter region." (PMID 31803620, 2019). "Moreover, the loss of expression of the COL4A5 and COL4A6 chains in colorectal cancer has been linked to the hypermethylation of their promoter regions." (PMID 39845732, 2025). "Previous research has reported the downregulation of COL4A5 and COL4A6 expression in colorectal cancer." (PMID 38907304, 2024). "Downregulation of COL4A5 and COL4A6 was correlated with metastasis in different cancers including melanomas, colorectal cancer, follicular thyroid cancer, prostate cancer, basal cell carcinoma, and breast cancer 48-53." (PMID 34104083, 2021).